GAD2 (glutamate decarboxylase 2)
Diseases named in the same sentence as GAD2 in open-access papers (continued):
Sharing a sentence is not in itself a finding about the gene and the disease.
infection (14 papers, 2006 to 2025). The state of being infected such as from the introduction of a foreign agent such as serum, vaccine, antigenic substance or organism. "On the other hand, infection with Fgf13-S partially hyperpolarized the interspike membrane potential (compared to Gad2-Fgf13 cKO), suggesting that FGF13-S increased the repolarizing K+ currents." (PMID 39773461, 2025). "Similar to the pattern in DD plants, expression of GAD2 was downregulated after Pst, Pst‐avrRpt2, or Pst‐hrcC‐ infection." (PMID 32458527, 2020). "In response to Pst‐avrRpt2 infection, there was only a ~42% reduction in GAD2 transcript levels, and only a ~100‐fold induction (from the very low basal level) in GAD4 transcripts." (PMID 32458527, 2020). "However, closer inspection showed that there were differences in the densities of the axons, which may be explained, in part, by the different extents of somatic infection, and the broader range of interneuron types likely to be infected in the GAD2-cre mice." (PMID 31507383, 2019). "Genetic evidence revealed that GAD1, GAD2, and GAD4 play important roles in both GABA biosynthesis and plant resistance in response to Pst‐avrRpt2 infection." (PMID 32458527, 2020). "Both Pst‐avrRpt2 infection and activation of MPK3/MPK6 suppress GAD2 expression and induce the expression of GAD1/GAD4." (PMID 32458527, 2020). "In response to Pst‐avrRpt2 infection, expression of GAD1 and GAD4 is induced, while expression of GAD2 is downregulated." (PMID 32458527, 2020). "We found that the expression of GAD2 is not suppressed in these mutants when inoculated with pathogen as it is in the wild type, which might be one reason for the slightly higher GABA level in these mutants after Pst‐avrRpt2 infection." (PMID 32458527, 2020).
psychiatric disorder (7 papers, 2013 to 2024). A disorder characterized by behavioral and/or psychological abnormalities, often accompanied by physical symptoms. "PRKCE interacts with several proteins encoded by genes of potential relevance to psychiatric disorders, including the glutamate decarboxylases (GAD1, GAD2), NMDA receptors (GRIN2D, GRIN1), and a metabotropic glutamate receptor (GRM5)." (PMID 23922650, 2013). "Finally, the expression of both GAD2 transcripts differed significantly between patients with psychiatric disorders compared to non-psychiatric controls." (PMID 26848839, 2016).
metabolic disease (1 paper, 2013). A congenital disorder (due to inherited enzyme abnormality) or acquired (due to failure of a metabolically important organ) disorder resulting from an abnormal metabolic process. "GAD2 is localized to the nerve terminal and is reversibly bound to the membrane of synaptic vesicles, which has been linked with lower birth weights and additional risk for metabolic diseases, whereas GAD1 is a cytosolic enzyme distributed throughout the organs and central nervous system." (PMID 24261884, 2013).
GAD2 also shares sentences with these, for which no sentence is quoted: Autoimmunity (61 papers); encephalitis (61); cerebellar ataxia (60); stiff-person syndrome (53); autoimmune encephalitis (48); neurological disorders (36); autoimmune disease (21); tumor (20); Ataxia (15); Hyperglycemia (14); temporal lobe epilepsy (11); autoimmune neurological diseases (7); Encephalopathy (7); insulinoma (7); vitiligo (7); paraneoplastic neurological syndrome (6); Seizure (6); thyroiditis (6); bipolar disorder (5); insomnia (5); lung carcinoma (5); pernicious anemia (5); Batten disease (4); breast carcinoma (4); celiac disease (4); cerebellar degeneration (4); diabetic ketoacidosis (4); epilepsy syndrome (4); hypothyroidism (4); meningoencephalitis (4).
A further 173 diseases each share a sentence with GAD2 in 4 papers or fewer.